CD4 (CD4 molecule)
Diseases named in the same sentence as CD4 in open-access papers (continued):
Sharing a sentence is not in itself a finding about the gene and the disease.
tumor (continued). "Specimens from cohort 2 were subjected to immunohistochemical analysis for the following markers: CD3, CD4, CD8, FOXP3, and PD-1 on tumor infiltrating lymphocytes (TIL) and PD-L1 on tumor cells." (PMID 30616523, 2019). "We found a decreased expression of CD4 mRNA in the TU region of patients with ADC and SCC, as compared to the respective CTR region as well as the PT region representing the tumour microenvironment of the lung." (PMID 30956278, 2019). "Lycopene treatment increased the CD4+/CD8+ ratio in the spleen and promoted IFNγ-expressing CD8+ T cells in tumor tissues." (PMID 30948928, 2019). "In contrast a rapid infiltration of CD4+ T cells, followed by DC and CD8+ T cells was observed at the tumor site when mice were injected with CIITA-tumors." (PMID 31417570, 2019). "Most importantly, we found that the percentage of CD4+CD28− and CD8+CD28− cells among tumor-infiltrated CD4 and CD8, respectively, were significantly lower in PEF-treated tumors in comparison with infiltrated CD4 and CD8 T cells in untreated tumors." (PMID 31717542, 2019). "In tumor-bearing mice treated with T-DM1, survival was reduced by depleting antibodies which inhibit the function of CD4+ and CD8+ T cells." (PMID 30755651, 2019). "Vaccination with irradiated cells overexpressing GM-CSF or IL-21 alone significantly inhibited tumor growth and led to significantly more CD4+ CD8+ T cells and fewer CD4+ Foxp3+ T cells in the spleen and xenograft." (PMID 31467912, 2019). "The ratios of intratumoral CD8/CD4, CD8/Treg, and CD4/Treg significantly increased after Erb-sumIL2 treatment; similar results were obtained in the MC38 tumor model." (PMID 31462678, 2019). "The T lymphocytes (CD4 and CD8) play an important role in eliminating tumor cells; this process is known as immune-surveillance." (PMID 31737570, 2019). "The frequency of CD3+ T cells in the tumor tissue (30.0%) was higher than the frequency of these cells in the splenocytes (21.1%), but the CD8/CD4 ratio was comparable in both tissues." (PMID 31131189, 2019). "Comparison of the different T-cell subsets revealed that the amount of CD4+ T cells, as a percentage of total CD3+ cells, was similar in the tumor and in peripheral blood." (PMID 29930558, 2018). "As suggested by Blankenstein, tumor suppression factors are meditated by activation of TAM class M1 in the tumor epithelial and stromal compartments and helper T cells (CD3 + CD4+) in the tumor epithelial compartment." (PMID 29871672, 2018). "Second, CD4+ T, CD8+ T and NK cells expressing CD57 antigen can produce more IFN-γ to inhibit the growth of tumor when stimulated." (PMID 29487719, 2018). "While several cell types contribute to anti-tumor responses, CD4 T-helper 1 (TH1) cells and CD8 cytotoxic T-lymphocytes (CTL), are critical in mediating anti-tumor immunity due to their ability to recognize tumor antigens and mediate tumor killing." (PMID 30967879, 2018). "In the B16.F1 melanoma model, intraperitoneal treatment with attenuated Salmonella led to increased infiltration of both CD4+ and CD8+ T cells into the tumor." (PMID 29765907, 2018). "On the surface of the CD4+CD25+ lymphocytes, Tag7 acts as a specialized receptor involved in the recognition of HLA-negative tumor cells." (PMID 29850628, 2018). "In a meta-analysis of patients with lung cancer, high levels of CD8, CD4 and CD3 T cell infiltration into the tumor stroma showed better overall survival, whereas high density of FOXP3+ T cell infiltration was a negative prognostic factor." (PMID 30229370, 2018). "These macrophages inhibited the proliferation of both CD4+ and CD8+ T cells in vitro, and promoted tumor growth mainly through PD-L1 in vivo." (PMID 30563569, 2018). "The CD4+ cells provide necessary factors for priming CD8+ cells and for the expansion of tumor-specific CD8+ TC cells." (PMID 30237863, 2018).
tumor (continued). "Of 8 patients with evaluable paired tumor biopsies, one patient with HPV+ HNSCC and the highest baseline GITR on CD4+ T cells showed a 2x increase in intratumoral CD8+ and tumoral PD-L1+ cells." (PMID 30400822, 2018). "Compared with the control group, depletion of CD8+ T cells completely abolished the tumor growth inhibition induced by TIGIT knockout, while CD4+ T cell depletion exhibited weaker impact on tumor growth." (PMID 30555485, 2018). "Another critical step in the anti-tumor immune response is the CD4+ and CD8+T cells homing to the primary tumor site." (PMID 29515996, 2018). "Tumor inhibition was also dependent on CD19, presumably B, cells, which is consistent with another study showing that a CD4+ T cell-driven antitumor response was also dependent on CD19 cells." (PMID 30135425, 2018). "In contrast, the accumulation of CD4+ CD25hi regulatory T cells (Tregs) contribute to immunosuppression in the TME and blunt productive anti-tumor responses, as demonstrated by depletion studies in preclinical models of PDAC." (PMID 30283732, 2018). "Patients with a high CD4/CD8 ratio have a poorer outcome, whereas a high tumor infiltrating lymphocytes (TIL)/Treg ratio is generally favorable." (PMID 29342108, 2018). "Our results demonstrated that LBP treatment prevented the increase of CD4+ CD25high Tregs and promoted infiltration of CD8+ T cells in tumor tissue." (PMID 29967800, 2018). "CD4+ Th1 cells produce high levels of IFN-γ and TNF-α upon antigen stimulation and take charge of cell-mediated immunity to intracellular pathogens and tumor cells, while CD4+CD25+ Tregs mediate immune suppression." (PMID 30309387, 2018). "Based on our previous data we assume that a single dose of PD1-CD28 fusion receptor-transduced CD4+ and CD8+ T cells would induce tumor regression in vivo, significantly lowering potential side effects due to systemic T cell activation." (PMID 30214445, 2018). "PD-L1 is expressed on the surface of activated CD4+ T cells, activated CD8+ T cells, and on tumor cells." (PMID 29420595, 2018). "In this way, we analyzed these checkpoints in CD4+ and CD8+ T cells, as well as their expression on tumor cells." (PMID 30356816, 2018). "In this study; however, we specifically conducted a syngeneic animal model to examine the real immune environment in which the CD4, CD8, and natural killer (NK) cells play important roles in ADSC-E7’-eGFP-mediated tumor inhibition." (PMID 30445793, 2018). "The ratios of CD3+CD8+ cytotoxic T cells, CD49b+NK cells, CD4+CD25+FoxP3+ Tregs and Gr1+CD11b+ MDSCs in tumor-DLN or spleen were examined by flow cytometry." (PMID 29301578, 2018). "The results of these experiments demonstrated the mutual dependence of CD4 and CD8 T cell responses, since these cells needed to act in concert to efficiently suppress tumor development and to allow for long term survival." (PMID 29032503, 2018). "We detected the density and distribution of CD8+ T cells, CD4+ T cells, Foxp3+ T cells and CD33+ MDSC infiltrating the tumor site." (PMID 30285868, 2018). "Intratumorally, both CD4+ and CD8+ TAC-T cells expanded, demonstrating a balanced anti-tumor attack." (PMID 30076299, 2018). "Intratumoral administration of an oncolytic adenovirus led to dramatic intratumoral infiltration of both CD4+ and CD8+ lymphocytes and sensitized the M109 tumor to the treatment of anti–PD-1 or anti–PD-L1 antibodies." (PMID 30409126, 2018). "Immunohistochemistry revealed co-localization of PD-L1 and PanCK in tumor areas, whereas stroma containing CD4 and CD8 positive lymphocytes was predominantly located surrounding the tumor tissue." (PMID 29535806, 2018). "Similar percentages of CD4+CD8α−FOXP3+ T cells were observed when comparing blood and tumor isolates (mean values: 10.1 and 12.9%)." (PMID 29930558, 2018). "Tumour cells are CD3+, either CD4+ (more commonly) or CD8+, or in rare instances CD4−/CD8−, whilst those expressing CD8 have a cytotoxic profile (TIA1+, granzyme B±)." (PMID 30305106, 2018).
tumor (continued). "The GBC tumor tissues were grouped into two categories, according to the degree of CD3+, CD4+, or CD8+ T cell infiltration and either high or low infiltration rate." (PMID 29499656, 2018). "The virus treatment increased the presence of CD3+ T lymphocytes, CD3+CD4+ helper T cells, CD3+CD8+ cytotoxic T cells and the effector T cell frequency, and decreased the amount of T regulatory cells in the tumor." (PMID 30400822, 2018). "We found that Sipa1−/− memory CD8+ T cells in tumor tissue further produce Ccl5 (Rantes), which shows potent TCR costimulatory activity for CD4+ T cells in addition to T-cell chemotactic activity." (PMID 29500416, 2018). "CXCL9 and CXCL10, agonists of the CXCR3, promote the recruitment of CD4+ Th1 lymphocytes, NK cells, and CD8+ cytotoxic T lymphocytes (CTL) to the TME, where they exert a potent anti-tumor activity." (PMID 30319638, 2018). "Here, we found that 53.9% (± 20.0%) of CD4+ TILs and 54% (± 16.9%) of CD8+ TILs expressed PD-1, at the time of isolation from the digested tumour samples." (PMID 30039427, 2018). "In the liver cancer study, the transcriptome of 5,063 FACS isolated T cells (CD4+ or CD8+) from peripheral blood, tumor, and adjacent normal tissues from 6 hepatocellular carcinoma patients was sequenced (Smart-seq2)." (PMID 30483257, 2018). "All studies, irrespective of the endolysosomal protein used, concluded that the increased cross-presentation enhanced CD4+ and CD8+ T cell activation and increased anti-tumor immunity in vitro and in vivo." (PMID 29867960, 2018). "CD4+ T cells play a key role in initiating and sustaining the CD8+ T lymphocyte-led immune responses directed against tumour cells." (PMID 29490633, 2018). "A histological examination revealed fibrosis and tumor cell death with an infiltration of CD8+ and CD4+ T-cells around tumor islets, findings that support the induction of an immune response by HF10." (PMID 30261620, 2018). "It was reported that the CD4+CD25+ Treg cell population is generally increased in the peripheral blood and tumor tissue of patients with stomach cancer, lung cancer, liver cancer, colon cancer, melanoma, and other types of cancer." (PMID 30517305, 2018). "Heat-shocked mouse B lymphoma cells were also capable of promoting anti-tumor immune responses, mostly mediated by CD8+ T cells, although CD4+ T cells were also necessary, and the exosomes promoted DC maturation." (PMID 29696022, 2018). "In this multiplex IHC analysis, we found that ibuprofen induced the most dramatic immune alterations at the tumor border with a trend for increased CD45+ cells, and significant increases in total CD3+, and CD8+ and CD4+ T cell compartments." (PMID 30285905, 2018). "The percentage of CD4+CD25+FoxP3+ Tregs and Gr1+CD11b+MDSCs were significantly increased in tumor microenvironment, and all these were attributed to the upregulation of TGF-β1." (PMID 29301578, 2018). "It has been previously demonstrated that in addition to the direct tumor lytic activity of CD8+ T cells, CD4+ T cells provide a protective function by cytokines secretion and inflammatory reactions." (PMID 30108590, 2018). "To compare pure DCIS and miCa by dominant immune response type at the tumour site, we derived a ratio (T/B ratio) between the cells representing cellular immunity (T-cells, CD8+ and CD4+) and the cells representing humoral immunity (B-cells, CD20+)." (PMID 29394917, 2018). "CD4 and CD8 T lymphocytes isolated from total splenocytes were obtained and cultured with tumor antigens to analyze the cytokine profile of tumor-specific T cells induced by vaccination." (PMID 30300366, 2018). "We found that LBP treatment inhibited the PD-1 expression on T-cell subsets, including CD4+CD25− and CD8+ T cells in tumor tissue." (PMID 29967800, 2018).
tumor (continued). "Conversely, in preclinical studies, the presence of immunosuppressive CD4+CD25+FOXP3+ regulatory T cells and immunosuppressive soluble factors inside the tumor corresponded with poor prognosis in MPM, due to suppression of anti-tumor immune responses." (PMID 29342862, 2018). "Cell sorting of tumor immune infiltrates indicated that SB225002 treatment reduced myeloid-derived suppressor cells (MDSC) and Treg cells, and increased CD8+/CD4+ T cells, NK cells, macrophages and dendritic cells." (PMID 29632317, 2018). "CD4+ and CD8+ T lymphocytes can enhance cancer immune-surveillance to inhibit tumour cell proliferation, invasion and metastasis." (PMID 29544476, 2018). "The tumor tissues were stained for VIP, CD8 and DAPI, while the splenocytes were analyzed via flow cytometry for levels of CD3, CD4+, CD8+, CD4+PD1+ and CD8+PD1+ T cells." (PMID 30400835, 2018). "The assessment of other immune cell populations in the tumor showed that in both models, the P2Et/P2Et groups had increased proportions of tumor-infiltrating MDSC-LC and a higher number of CD4+ and CD8+ T cells than the other groups." (PMID 30234017, 2018). "Transient expansion of effector CD4+, CD8+ T and NK cells and increased vaccinal and tumour-specific T cell responses were also observed in some of the patients." (PMID 29396470, 2018). "The antitumor effects induced by anti-CD4 depleting monoclonal antibodies (anti-CD4 mAb) were found to be mediated by CD8+ cytotoxic T lymphocytes (CTLs), which increased in the draining lymph node (dLN) and tumor after anti-CD4 mAb treatment." (PMID 30733724, 2018). "Percentages of CD11c+ dendritic cells, B220+ B cells, CD4+ and CD8+ T cells, forkhead box protein (FoxP3+) regulatory T cells, and NK1.1+ natural killer (NK) cells were the same in spleens of MCA205 tumor-bearing WT and S100A4−/− mice." (PMID 29556233, 2018). "Comparative analysis of the immune cells infiltrating the primary tumor and the SC mts revealed an increase mainly of CD8+, CD4+, and CD20+ lymphocytes." (PMID 29774030, 2018). "The results from the TILs revealed a significantly stronger CD8+ T-cell tumor infiltration, a higher CD8+/CD4+ T-cell ratio, and higher CD8+ PD1−/Treg-cell ratio in the group of pIL12 GET." (PMID 30544810, 2018). "Here, gemcitabine with FGK45 treatment induced a CD4+ and CD8+ T cell infiltration into subcutaneous tumor but only CD4+ infiltration into endogenous tumor." (PMID 30158932, 2018). "CD4+ TIL persisted in vivo and demonstrated a MHC class II-restricted response to autologous tumor, marked by a Th1 polarized cytokine profile." (PMID 30400835, 2018). "Tumor-infiltrating CD8+ and CD4+ T lymphocytes induce cytotoxic cell death and inhibit tumor cell proliferation and migration in antitumor immune reactions." (PMID 30539019, 2018). "In both cases, antitumor activity was related to the induction of antitumor CD4+ and CD8+ mediated immune response, with an increased tumor cell lysis and production of proinflammatory cytokines." (PMID 30510968, 2018). "The tumor-bearing mice in the model group had higher percentages of CD8+ PD-1+ T cells and CD4+ CD25− PD-1+ T cells in the spleens than those in the control group." (PMID 29967800, 2018). "The presence of both the CD4+ TH cells and CD8+ TC cells in the periphery is very important to control tumor progression and metastasis." (PMID 30237863, 2018). "Subcutaneous B16F10, 4T1 or CMS5m tumour was treated with DUC18 CD8 EVs, BALB CD8 EVs, BALB CD4 EVs or BALB TB CD8 EVs at 10, 13 and 16 days after tumour inoculation." (PMID 29382847, 2018). "CCR5 is highly expressed on tumor infiltrating CD8+ T cells, conventional and regulatory CD4+ T cells, and on the surface of MDSC." (PMID 30420855, 2018). "This is supported by TLR2 ligand-conjugated HPV long peptides which can strongly activate CD4 and CD8 T cells from tumor-draining lymph nodes of cervical cancer patients." (PMID 29755468, 2018).
tumor (continued). "The percentages of activated CD4+Foxp3− and CD8+IFN-γ+ T cells from tumours receiving vvDD-IL-2-RG treatment were increased, compared to those treated with other viruses." (PMID 30410056, 2018). "The actual numbers of both CD4+ and CD8+ T cells were also greater in the tumor tissues of Sipa1−/− mice, the majority showed memory phenotype." (PMID 29500416, 2018). "Tα1-Fc displayed a more effective antitumor activity in the 4T1 and B16F10 tumor xenograft models by upregulating CD86 expression, secreting IFN-γ and IL-2, and increasing the number of tumor-infiltrating CD4+ T and CD8+ T cells." (PMID 30120362, 2018). "Very interestingly, the combined blockade of IL-6 and PD-1/PD-L1 axe provides the synergistic effects not only on CD4+ Th1 response but also on the recruitment and function of CD8+ T cells in the tumor and its microenvironment." (PMID 30587227, 2018). "(C) One field from (B) at the tumor-normal junction demonstrating staining for S100-postive malignant cells, α-SMA positive stroma, T lymphocytes (positive for CD3, CD4 and CD8), and the proliferation marker phospho-RB (pRB)." (PMID 29993362, 2018). "We have found that the presence of fewer CD4+ TH cells and CD8 TC cells in the TME correlates with larger tumor sizes in a2V-KO mice." (PMID 30237863, 2018). "The main focus is on the currently existing knowledge about the CD4 and CD8 T lymphocyte interplay that mediates the control of tumor growth." (PMID 29032503, 2018). "The adaptive immune system is mainly represented by tumor infiltrating lymphocytes comprising CD8+ cytotoxic T-lymphocytes and CD4+ T-helper lymphocytes." (PMID 30509242, 2018). "In summary, the SVX vaccine allowed to generate both CD4+ and CD8+ specific T-cell responses, leading in mice to high therapeutic efficacy in various tumor models." (PMID 30483475, 2018). "Our results showed that B-9-3, in both standard and cancer mice, enhanced the level of CD4+ and CD8+ T cells in the circulatory and splenic compartments besides the primary tumor site." (PMID 30079021, 2018). "After vaccination of B1610 tumor mice with PSPEI-PAA nanocomplex, single cell suspension of the isolated tumor and tumor draining lymph node were then prepared for the assessment of the matured DCs, CD8+, CD4+ and CD4+FOXP3+ T lymphocytes." (PMID 30960988, 2018). "Thus, tumor-specific anergic CD4+ T cells may also exist in humans." (PMID 29844317, 2018). "Mice depleted of either CD4+ T cells or the combination of CD4+/CD8+ T cells, were unable to mount an effective anti-tumor response." (PMID 30563566, 2018). "We detected clustered CD4+ T cells, CD19+ B cells, and scattered CD8+ T cells in the fatty change tissues and late tumor tissues." (PMID 30526672, 2018). "Immunization with T7 − MB in combination with 5-FU chemotherapy reduced tumor sizes and extended long-term survival rates, mainly by improving T cell responses, including CTLs, CD3+/CD8+ and CD3+/CD4+ T cells." (PMID 29739434, 2018). "These mice showed durable response and increased CD4+ and CD8+ effector memory on tumor rechallenge." (PMID 30294332, 2018). "Tumor infiltrating lymphocytes (TILs) which include CD8+ cytotoxic T lymphocytes (CTLs), CD4+ T helper lymphocytes (Th), CD4+ regulatory T lymphocytes (Treg), γδT cells, and B-cells." (PMID 30356678, 2018). "The outcomes observed with combined PD-1 and CTLA-4 blockade were found to correlate with an increase in CD4+ effector T cell (CD4+ Teff) to Treg cell ratio and CD8+ T cell to Treg cell ratio in tumor tissue." (PMID 29769148, 2018). "In line with the higher density of Foxp3 on the CD39+ Treg population in the tumor, our data indicate that CD39+ Treg more frequently belong to the CD4+CD45RA−Foxp3hi activated Treg population, compared to CD39− Treg." (PMID 30651930, 2018). "Our data show how CD4+ and CD8+ CM and effector T cells are a bellwether of responses to checkpoint inhibitors, presumably because all of them contribute to the anti-tumor responses." (PMID 30123214, 2018).